SOX2 (SRY-box transcription factor 2)
Diseases named in the same sentence as SOX2 in open-access papers (continued):
Sharing a sentence is not in itself a finding about the gene and the disease.
myeloma (10 papers, 2011 to 2023). "Stemness-associated transcription factors, such as Sox2, Oct3/4, Nanog, Klf4, β-catenin and c-Myc, play major roles in the maintenance of myeloma stem cell-like SP cells in MM78,79." (PMID 36289430, 2022). "Long non-coding RNA Sox2 overlapping transcript (SOX2OT) promotes multiple myeloma progression via microRNA-143-3p/c-MET axis." (PMID 38153182, 2023). "Upon fusion of MSCs with multiple myeloma cells, expression of Nanog, Sox2 and Oct4 increased significantly, and the drug resistance of the fusion cells was increased." (PMID 32632040, 2020). "Sox2 expression has been shown to correlate with the myeloma-propagating capability in myeloma cell lines." (PMID 31684964, 2019). "In particular, this database reports an expression of SOX2 in plasma cells and myeloma cells, as confirmed by our data." (PMID 22190969, 2011). "Out of all samples consecutively collected from our myeloma patients, 2% (68/1094) were positive for anti-SOX2 IgG antibodies." (PMID 22190969, 2011). "To prove the presence of SOX2 on the protein level, we have performed flow cytometry analysis of myeloma cell lines and of plasma cells of healthy donors, all of which we found positive for SOX2 by RT-PCR." (PMID 22190969, 2011). "Overall, myeloma patients showed a significantly higher frequency of anti-SOX2 antibodies than healthy controls (P < 0.05)." (PMID 22190969, 2011). "We found that the IgG antibodies in the patients' sera recognized both the recombinant SOX2 protein and SOX2 protein expressed by a myeloma cell line (U266) shown to be positive for SOX2." (PMID 22190969, 2011). "We next screened a large number of sera (n = 1094) consecutively collected from myeloma patients (n = 196) as well as sera from healthy blood donors (n = 100) for antibody responses against SOX2." (PMID 22190969, 2011). "This intriguing phenomenon may be related to epitope- spreading since CD19 and Sox2 are co-expressed in myeloma-propagating cells (MPC) which are targeted by CTL019 cells." (PMID 31684964, 2019). "Eventually, knowledge gained through such studies will help us to decide whether SOX2 represents a promising prognostic or therapeutic target for patients with multiple myeloma." (PMID 22190969, 2011). "The questions whether SOX2-specific autoantibodies merely represent an epiphenomenon, are related to graft-versus-host effects or participate in the immune control of myeloma needs to be answered in prospective studies." (PMID 22190969, 2011). "Importantly, all of the myeloma cell lines, all peripheral, and one of two bone marrow-derived plasma cell samples were also found positive for SOX2 on the protein level." (PMID 22190969, 2011). "However, it is unclear if SOX2-specific antibodies also develop in established multiple myeloma (MM)." (PMID 22190969, 2011). "Since myeloma treatment, particularly stem cell transplantation, has immune-modulating properties, we finally investigated the relationship between therapeutic interventions and the occurrence of SOX2-specific antibodies in the myeloma patients." (PMID 22190969, 2011). "Furthermore, SOX2 mediates drug resistance and renewal of myeloma, skin and bladder cancers." (PMID 32483123, 2020). "Therefore, in this study, we only demonstrated that ALKBH5 increased the percentage of SP cells and CD138-/CD34- myeloma stem cells by activating cancer stem cell related HIPPO pathway signalling and promoting the expression of pluripotency factors NANOG, SOX2 and OCT4." (PMID 35414790, 2022). "While plasma cells in general might indeed express comparably high levels of SOX2, we believe that SOX2 is by no means tumor or myeloma specific." (PMID 22190969, 2011). "Importantly, we did not detect any significant differences in BM expression of SOX2 between myeloma patients and healthy donors." (PMID 22190969, 2011).
myeloma (continued). "As suggested by the comparable expression of SOX2 in normal and malignant plasma cells and its broad expression in different healthy tissues, copy numbers of SOX2 RNA as measured by quantitative PCR did not correlate with the percentage of myeloma cells within the BM of our MM patients." (PMID 22190969, 2011).
endometriosis (9 papers, 2014 to 2024). The growth of functional endometrial tissue in anatomic sites outside the uterine body. "As highlighted above, another transcription factor found in cancer, SOX2, was also found to be highly increased in the stromal component of ectopic progenitor cells inside endometriosis implants." (PMID 39684461, 2024). "Several research studies have reported that the expression of stemness genes such as OCT-4 and SOX-2 was increased in patients with endometriosis." (PMID 35059465, 2022). "The expression of stemness-related genes, namely, Oct4, Sox2, and Nanog, was markedly increased in the ectopic endometrium of patients with endometriosis, and thus supports a role for stem cells in endometriosis pathogenesis." (PMID 35409294, 2022). "Compared to the control group, SOX2 mRNA and protein expression was significantly higher in the eutopic endometrium of participants in the endometriosis group." (PMID 24884521, 2014). "SOX2 mRNA and protein expression was significantly higher in the eutopic endometrium of participants in the endometriosis group, supporting a stem-cell origin of endometriosis." (PMID 39684461, 2024). "In the endometriosis group, SOX2 and NANOG mRNA and protein expression were significantly increased in ectopic endometrium compared with eutopic endometrium; there was a trend towards lower OCT4 mRNA expression and higher OCT4 protein expression in ectopic endometrium." (PMID 24884521, 2014). "The aberrant SOX2 expression in ovarian endometriosis in our study, consistent with that reported previously, may indicate a stem cell origin of endometriosis." (PMID 24884521, 2014). "The role of multiple other stem cell markers has been explored, such as SOX2 and NANOG in endometriosis." (PMID 39684461, 2024). "Our findings are in accordance with other endometriosis literature identifying downstream LIF targets NANOG, OCT-3/4, and SOX2 to be elevated in ectopic lesions compared to control endometrium." (PMID 37033980, 2023). "In this study, we analyzed the mRNA expression of REX-1 stemness gene and reconsidered three other stemness genes SOX-2, NANOG, OCT-4 in women with endometriosis compared to normal endometrium." (PMID 31417979, 2018). "The transcription pluripotency factors SOX2 and NANOG were overexpression in ovarian endometriosis, their role in pathogenesis of endometriosis should be further studied." (PMID 24884521, 2014). "A larger sample size and the functional research of SOX2 and NANOG in pathogenesis of endometriosis is anticipated in our further study." (PMID 24884521, 2014). "Compared to those with I/II endometriosis, increased mean gene expression in endometriotic tissue from women with III/IV endometriosis was observed for MMP7 (0.10 vs. 0.00), FUT8 (1.14 vs. 0.02), and SOX2 (1.51 vs. 0.36)." (PMID 38674005, 2024). "SOX2 expression has been shown to be significantly increased in endometriosis compared to secretory endometrium of patients without endometriosis." (PMID 27881125, 2016). "Analysis of eutopic endometrial cells collected from the menstrual blood of patients with and without endometriosis revealed that endometriosis patients had higher mRNA expression of OCT4 and SOX2 than normal controls." (PMID 27881125, 2016). "The mean relative expressions of OCT-4, NANOG, and SOX-2 were significantly higher in ectopic endometrium compared with eutopic and normal endometrium (p = 0.041), but the REX-1 mRNA increase was not significant between endometriosis and control groups." (PMID 31417979, 2018). "The transcription levels of OCT-4, NANOG, and SOX-2 mRNA were significantly increased in ectopic lesions compared with eutopic and control group (p = 0.041, p = 0.035, p = 0.048), although the REX-1 mRNA increase was not significant between endometriosis and control groups." (PMID 31417979, 2018).
gastric tumor (9 papers, 2013 to 2021). "SOX2 was expressed in 52% of the gastric tumors and was significantly associated with male gender, T stage and N stage." (PMID 25300947, 2014). "Accordingly, NOX1/ROS signaling may promote an increase in SOX2-exressing undifferentiated epithelial cells, contributing to the development of gastritis-associated hyperplasia and gastric tumors." (PMID 30700829, 2019). "In gastric tumor cells, Sox-2 and Oct-4 play main roles in the proliferation, migration, invasion, and tumorigenicity." (PMID 34885925, 2021). "Similar to our studies, elevation of SOX2 has also been reported to inhibit the growth of gastric tumor cells." (PMID 32998722, 2020). "Taken together, these results indicate that NOX1/ROS pathway induces increase of SOX2 expression in gastric tumor cells." (PMID 30700829, 2019). "In both studies, SOX2 was substantially overexpressed in gastric tumor cell lines that endogenously express relatively little SOX2." (PMID 28388544, 2017). "For example, stable overexpression of SOX2 in the gastric tumor cell line N87 was reported to increase growth both in vitro and in vivo." (PMID 28388544, 2017). "Although, elevated miR-126 expression and low SOX2 expression was observed in several gastric cancer tumor specimens, low miR-126 expression was accompanied by low SOX2 expression in several other gastric tumor specimens." (PMID 28388544, 2017). "SOX2, CDX2, MUC5AC and MUC2 expression were assessed in 201 gastric tumors by immunohistochemistry." (PMID 25300947, 2014). "Consistent with this, we found that SOX2, POU5F1 (a gene encoding OCT4) and ITGA6 were all strongly expressed in human gastric tumors examined, except that SOX2 was not expressed by MKN74 cell line." (PMID 24015244, 2013). "In addition, these investigators reported that miR-371-5p downregulated a luciferase reporter gene construct containing a short sequence from the SOX2 3’UTR; whereas blocking expression of this miR in gastric tumor cell line increased SOX2 expression and cell proliferation in vitro." (PMID 28388544, 2017). "Furthermore, these investigators reported low SOX2 expression and elevated miR-126 in some gastric tumor specimens, but the results reported do not show a clear pattern." (PMID 28388544, 2017).
laryngeal squamous cell carcinoma (9 papers, 2014 to 2025). A squamous cell carcinoma that arises from the larynx. "The expression of SOX2 affects the OS of patients, acting as an independent prognostic factor for laryngeal squamous cell carcinoma tissues of patients, indicating that SOX2 may present as a useful prognostic marker and a potential therapeutic target for laryngeal squamous cell carcinoma patients." (PMID 41463190, 2025). "Knockdown of USP34 could significantly inhibit laryngeal squamous cell carcinoma (LSCC) cell growth, but overexpression of SOX2 could reverse this effect." (PMID 40599863, 2025). "Moreover, in cisplatin-resistant laryngeal squamous cell carcinoma (LSCC) cells, USP34’s interaction with SOX2, a key CSC- and EMT-related transcription factor, decreases SOX2 polyubiquitination and augments LSCC cell sensitivity to cisplatin." (PMID 38702734, 2024).
neuroendocrine tumors (9 papers, 2013 to 2025). "SOX2 is a transcription factor crucial for maintaining pluripotency in stem cells, frequently demonstrating nuclear staining in neuroendocrine tumors of the bladder." (PMID 40735045, 2025). "Neuroendocrine tumors expressing markers like SOX2, Synaptophysin, and Chromogranin A generally exhibit high aggressiveness and poor prognosis." (PMID 40735045, 2025). "Next, we identified and characterized the bronchial carcinoid TIC population by the expression of stemness markers, ALDH1, CD44, Oct-4, Sox-2 and Nanog, appropriate markers based on previous studies on neuroendocrine tumors." (PMID 31470802, 2019). "Given the role of SOX2 in neural stem cell renewal, its expression have been reported in other types of neuroendocrine tumor." (PMID 26673008, 2016). "SOX2 and INSM1 are frequently expressed in MCC and other neuroendocrine tumors and are regarded as markers for a neuroendocrine phenotype." (PMID 34667274, 2022).
renal cell carcinoma (9 papers, 2015 to 2024). "Overexpression of miR-200c-3p obviously suppresses proliferation, migration/invasion, and induced apoptosis of renal cell carcinoma cells through targeting SOX2 via modulating the wnt/β-catenin signaling pathway." (PMID 34524611, 2021). "For example, miR-200c-3p showed inhibitory effects of migration and invasion of renal cell carcinoma cells through targeting SOX2." (PMID 34524611, 2021). "Additionally, in a recent report, SOX2 and OCT4 have been implicated in poor prognosis of renal cell carcinoma, and their coexpression contributed to immunosuppressive phenotype." (PMID 38429272, 2024).
retinoblastoma (9 papers, 2013 to 2025). A malignant tumor that originates in the nuclear layer of the retina. "In retinoblastoma tumor, stemness-related SOX2 was associated with eyes with higher VEGF-A expression and tumor invasiveness." (PMID 32144236, 2020). "Enhanced SOX2 expression in Rb tissues and peripheral blood was closely associated with the clinicopathological characteristics of Rb." (PMID 25663891, 2015). "Small populations of retinoblastoma cells have been found to express stem cell–associated markers SOX2, aldehyde dehydrogenase 1, p63, and ABCG2, and to exclude Hoechst dye." (PMID 23559850, 2013). "Robust SOX2 expression is frequently observed in clinically aggressive, poorly differentiated retinoblastomas, correlating with invasiveness and stemness, further validating the primitive progenitor phenotype identified in our model." (PMID 40943594, 2025). "In retinoblastoma tumors, stemness‐related SOX2 is usually accompanied by higher VEGFA expression and tumor invasion." (PMID 36708044, 2023). "It has been reported that increased expression of Sox2 is positively correlated with angiogenic factors in retinoblastoma tissues, implying Sox2 have a role in tumor angiogenesis." (PMID 32541667, 2020). "The correlation between SOX2 expression and the clinicopathological characteristics of Rb was analyzed using χ2 tests." (PMID 25663891, 2015). "The present study aimed to investigate the association between the expression of sex-determining region Y box 2 (SOX2) in retinoblastoma (Rb) tissues and peripheral blood, and the clinicopathological characteristics of Rb." (PMID 25663891, 2015). "The results of the present study indicate that the SOX2 protein, as a key transcription factor in the embryotic development and tissue cell differentiation, has an important role in the incidence and development of Rb." (PMID 25663891, 2015). "The peripheral blood results suggested that SOX2 gene expression may be clinically useful for the early diagnosis and treatment of children with Rb." (PMID 25663891, 2015). "The present study indicates that SOX2 has an important role in the incidence and development of Rb." (PMID 25663891, 2015). "This together with lack of expression of other well-known RPCs markers such as SOX2, SFRP2, HES1 and HES5, excludes RPCs as cell of origin for retinoblastoma." (PMID 34003213, 2021).
Alzheimer disease (8 papers, 2019 to 2025). A progressive, neurodegenerative disease characterized by loss of function and death of nerve cells in several areas of the brain leading to loss of cognitive function such as memory and language. "Sox2 deficiency causes neurodegeneration and impaired neurogenesis in the adult mouse, such as intervening Alzheimer's disease development by decreasing the β-amyloid precursor protein, protecting neurons from excitotoxicity by BnNOS-Sox2-Shh axis." (PMID 33414894, 2020). "Reduction in SOX2 positive NSCs detected in the hippocampus of Alzheimer’s disease patients is correlated with the severity of the disease or the patient’s cognitive capacity." (PMID 33867936, 2021). "For example, SOX-2 expression is decreased in the brain of the transgenic Alzheimer’s disease mouse model, as well as in the brains of Alzheimer’s disease patients." (PMID 31980673, 2020). "In our previous work, we analyzed the expression of selected members of SOXB group (SOX1, SOX2, and SOX21) in the hippocampus of 2 months old 5xFAD mice, which represent a transgenic model of Alzheimer’s disease." (PMID 33867936, 2021).
astrocytomas (8 papers, 2013 to 2025). "This is also supported by the recent finding that SOX2 repression is an early driver of gliomagenesis that blocks the differentiation of neural stem cells in an in-vitro model of low-grade astrocytomas." (PMID 29631562, 2018). "We attempted to identify HIF-1α-regulated quiescent stem-like tumor cells in astrocytoma tissues using the following immunophenotypes as indices: SOX2+ HIF-1α+ RNApII-S2P-/low or NANOG+ HIF-1α+ RNApII-S2P-/low." (PMID 26799577, 2016). "SOX2 expression levels were compared to ID4 levels to verify the degree of their co-expression in human diffusively infiltrative astrocytomas." (PMID 23613880, 2013). "Positive correlation was found when comparing ID4 relative expression of infiltrative astrocytomas with SOX2 (r = 0.50; p<0.005), SOX4 (r = 0.43; p<0.005) and OCT-4 (r = 0.39; p<0.05)." (PMID 23613880, 2013). "iPSC lines were first differentiated to forebrain-patterned SOX2+/NESTIN+/SOX10− neural progenitor cells (NPCs) and then to GFAP+ astrocytes, the cell-of-origin of astrocytoma, using a modified astrocyte differentiation protocol." (PMID 36973285, 2023). "This pattern was maintained in secondary GBM and further confirmed by immunohistochemistry, suggesting a role for ID4, SOX2 and SOX4 in early astrocytoma tumorigenesis." (PMID 23613880, 2013). "Importantly, we observed that the tumor cells in the center zone displayed a prominent enrichment of stem cell markers Sox2 and Sox9, but did not express differentiated cell markers Olig2, CC1, S100β, and PDGFRα as observed in oligodendrocytoma and/or astrocytoma." (PMID 33863883, 2021).